BRAF (B-Raf proto-oncogene, serine/threonine kinase)
Diseases named in the same sentence as BRAF in open-access papers (continued):
Sharing a sentence is not in itself a finding about the gene and the disease.
cancer (continued). "Since a CDK (cyclind-dependent kinase) inhibitor also showed activity against SUR cells, the combination of HDAC inhibition with CDK inhibition appears to be promising in terms of concomitant apoptosis induction and cell cycle arrest in resistant BRAF-mutant cancers." (PMID 39935431, 2025). "However, they retain the ability to transform into malignant tumors if BRAF-induced senescence is suppressed or reversed." (PMID 40643463, 2025). "A pivotal regulatory milestone occurred in 2017 when the U.S. FDA approved vemurafenib for patients with BRAF V600E mutation–positive cancers, irrespective of tumor histology." (PMID 41225614, 2025). "Considering that BRAF kinase inhibitors or ICBs could directly regulate the coagulome of cancer cells, further studies testing the effects of medical treatments in patients with metastatic SKCM are required." (PMID 40003901, 2025). "Notably, Patient 63 had a KRAS G12V, SMAD4, GNAS, and KMT2C mutant-positive PDAC with liver metastases while Patient 64′s cancer was BRAF V600E-positive, and they had also undergone treatment with experimental BRAF and MEK inhibitors." (PMID 39941724, 2025). "The implementation of the National Genomic Test Directory for Cancer in England and access for all patients to NGS panels may provide greater information on the incidence of non-BRAF-V600E mutations, as well as data for NRAS and KIT." (PMID 40902091, 2025). "Although the expression of UBE2K is known to have a prognostic value in HCC, any potential role of UBE2K in BRAF-mutated cancer has not been established." (PMID 40080754, 2025). "Mutations occurring in cytoplasmic molecules, such as tyrosine kinase domains of receptors, KRAS2, PI3KCA, and BRAF, could be related to the inflammatory signaling cascades leading to cancer initiation if they occur before the advent of cancer stem cells." (PMID 39857984, 2025). "RAS mutations are considered weak as they are common in benign thyroid neoplasms and other cancers, whereas RET, NTRK, and ALK rearrangements, along with mutations in BRAF, EIF1AX, and the TERT promoter, are termed strong and are often associated with malignant tumors." (PMID 39744583, 2025). "In ITNs with isolated non-V600E BRAF and no other genetic alterations, one-third were benign, and all cancers were ATA low risk." (PMID 40075589, 2025). "In ITNs with isolated non-V600E BRAF and no other genetic alterations, one-third were non-malignant, and all cancers were ATA low risk." (PMID 40075589, 2025). "The B-rapidly accelerated fibrosarcoma (BRAF) gene plays a crucial role in activating the mitogen-activated protein kinase (MAPK) pathway, pivotal for cellular growth and differentiation, and is frequently mutated across various cancers." (PMID 40141188, 2025). "Furthermore, these therapies streamline drug development by enabling unified interventions for diverse cancers sharing common genetic drivers, such as BRAF V600E, HER2, NTRK fusions, and ROS1 rearrangements." (PMID 40075649, 2025). "Historically, type 1 RAF inhibitors (RAFi, vemurafenib, dabrafenib and others), which selectively target monomeric BRAF V600 mutants, have been ineffective for BRAF wild-type and non-V600 mutant cancers due to the paradoxical activation of ERK signaling through induction of RAF dimerization." (PMID 41023593, 2025).
cancer (continued). "Furthermore, BRAF and EGFR mutations are critical for optimizing targeted therapies in cancer patients." (PMID 40283283, 2025). "Overactivation of BRAF plays a key role in the unregulated growth that drives cancer formation." (PMID 38473384, 2024). "NF-2, a negative regulator of YAP signaling, was identified as a gene associated with cancer cell sensitivity to BRAF inhibitor, which indicates that YAP signaling could participate in BRAF inhibitor resistance." (PMID 38164167, 2024). "Finally, ASN007, an ERK1/2 inhibitor, is being tested in patients with BRAF fusion or non-V600 mutations to assess the effects of direct ERK inhibition, a downstream effector in BRAF-mutated cancers." (PMID 38790167, 2024). "The specificity of PDT could prove to be useful in the treatment of BRAF-mutant cancers, especially in combination with other treatment strategies." (PMID 38539548, 2024). "Another interesting observation is the upregulation of the cancer stem cell marker, a cluster of Differentiation 133 (CD133), which determines the poor overall survival in colorectal cancer (CRC) and is regulated by the mutation of KRAS or BRAF." (PMID 39056802, 2024). "Importantly, reversible ATP-competitive inhibitors targeting ERK1/2 have been shown to be effective in cancer cells and tumors with acquired resistance to BRAF and MEK inhibitors." (PMID 38537148, 2024). "It is well known that this type of cancer affects more women than men regardless of the BRAF mutation status, which is also present in our study." (PMID 39767732, 2024). "Notably, genes identified in these metastatic patients—BAP1, BRAF, and EGFR—have been previously reported in association with cancer metastasis." (PMID 38893126, 2024). "Effective targeted therapy strategies have not yet been established for cancers with non-V600 BRAF mutations." (PMID 38275886, 2024). "Imbalanced TEADs transcriptional output leads to the signal enhancement of many oncogenes, including KRAS, BRAF, LKB1, NF2, and MYC, and subsequently facilitates tumor progression, metastasis, cancer metabolism, and immunity, and serving as the hallmark of cancer." (PMID 38607003, 2024). "In our previous study, we found resistance of BRAF mutant cancer cells to HAMLET." (PMID 38256402, 2024). "We demonstrated that driver genes (BRAF, RET and TERT, etc.)are co-mutated with other genes, such as DNA damage repair genes and metabolism related genes, thus forming a co-mutation pattern observed more frequently in cancer tissues than benign nodules." (PMID 38886866, 2024). "Notably, cancers with high levels of this ECM signature not only exhibit activated TGFβ signaling in CAFs but also carry distinct genomic alterations, including BRAF and SMAD4 mutations." (PMID 38731846, 2024). "When evaluating alteration class amongst BRAF GOF cancers, class I mutations were more common in BRAF-altered CRC compared to non-CRC GI malignancies (75% vs. 28%, p < 0.001)." (PMID 38791902, 2024). "Nonetheless, our findings indicate that CGP testing and liquid biopsy in BRAF-mutant cancer may offer valuable insights into determining treatment strategies." (PMID 38962037, 2024). "Moreover, inhibitors of this class induce paradoxical activation of MAPK signaling in both BRAF-wild type normal and cancer cells." (PMID 38731852, 2024). "Our findings suggest that MEK inhibitors, which are FDA-approved for oral administration for multiple BRAF-driven cancers, could be therapeutic for GD as well as DD." (PMID 39325541, 2024). "Besides the secondary EGFR mutations, amplification, loss, and mutation of some other cancer-related genes also contribute to gefitinib resistance, such as MET, HER2, BRAF, and PIK3CA." (PMID 38472205, 2024).
cancer (continued). "Several mechanisms have been proposed that TSH stimulation, proto-oncogenes such as BRAF mutations, and RET/PTC rearrangements may promote cancer development or growth." (PMID 39568807, 2024). "Notably, there are ten BRAF mutant tumors with the pathological diagnosis of undifferentiated or poorly differentiated cancer." (PMID 39235852, 2024). "Cancer cell lines harbouring a c-RAF mutation or a non-V600 B-RAF mutation (not an A-RAF mutation), were significantly more dependent upon c-RAF than those that harbour a BRAF V600 mutation." (PMID 38637546, 2024). "This strongly suggests that BRAF testing could be a valuable tool in diagnosing cancer in cases of indeterminate cytology." (PMID 39768693, 2024). "In BRAF-mutated cancers, resistance to BRAF inhibitors frequently involves reactivation of the MAPK pathway through either downstream mutations (e.g., MEK) or BRAF splice variants that promote dimerization, circumventing BRAF inhibition." (PMID 39518080, 2024). "Consequently, when comparing malignant tumors between Bethesda III and IV categories, Bethesda III cancers exhibited a higher prevalence of the aggressive BRAF V600E mutation." (PMID 39766147, 2024). "In prognostic terms, CRC patients possessing BRAF exon 15 p.V600E mutations display lower DFS, OS, and cancer-specific survival (CSS) when compared to non-BRAF-mutant CRC regardless of disease stage or chemotherapeutic intervention." (PMID 38539548, 2024). "However, according to clinical research, only approximately half of cancer patients respond to single-drug treatment with BRAF inhibitors." (PMID 38193944, 2024). "Both EMN and MK have been infrequently described as drug-related toxicities in cancer patients treated with BRAF (v-Raf murine sarcoma viral oncogene homolog B)-targeted therapies but have not been documented to occur simultaneously at the onset of anti-BRAF medication." (PMID 39479087, 2024). "In addition to MEK, BRAF is another kinase that plays a key role in the MAPK signaling pathway, and its mutations are implicated in the development of several cancers." (PMID 39728071, 2024). "Consequently, combined administration of BRAF and MEK inhibitors (MEKi) is the most common approach for the treatment of cancers carrying a BRAF V600E substitution." (PMID 38612902, 2024). "It is realistic to think that evidence about metabolism could also be valuable in monitoring and predicting responses to other cancers and treatment modalities, such as BRAF and MEK inhibitors and immunotherapy." (PMID 38254853, 2024). "However, hyperactivation of this signaling pathway causes excessive cell proliferation and culminates in the pathogenesis of human cancers, which has been exemplified by various oncogenic mutations in RAS and BRAF genes." (PMID 38791574, 2024). "Along with investigating BRAF and MEK/ERK in the treatment of BRAF-mutant cancers, researchers are looking into the role of other factors that may affect the emergence of resistance to BRAF inhibitors." (PMID 38539548, 2024). "Conversely, no targeted therapy treatments have been approved for cancers with Class 2 and 3 non-V600 BRAF mutations or BRAF fusions—which comprise approximately 35% of all oncogenic BRAF alterations in adult solid tumors." (PMID 38275886, 2024).
cancer (continued). "BRAF-induced MAPK-ERK activation may not be controlled with MEK inhibition only, and may require combined MEK and BRAF inhibition, whereas the MAPK-ERK activation can be modulated with MEK inhibition alone more readily in RAS-mutation-initiated cancers." (PMID 38999211, 2024). "In a recent in vitro and animal study we demonstrated that BRAF/MEK inhibitors could induce strong therapeutic responses in cancer cells harboring both BRAF V600E and mutant TERT promoter through causing robust apoptosis but not cells harboring WT TERT." (PMID 38735658, 2024). "This phenotype is concordant with the mutual exclusivity of activating mutations within KRAS and BRAF in patient CRC samples (P < 0.001), highlighting that the drug addiction phenotype is dependent on pre-existing mutations in the cancer cell." (PMID 39424923, 2024). "We have shown previously that depletion of the MEK/ERK kinase, BRAF decreases the permeability of the endothelial monolayer and the transmigration of cancer cells in response to thrombin and this is related to the role of BRAF exerted on the dynamical reorganization of the actin cytoskeleton." (PMID 39457016, 2024). "Based on these observations, we then hypothesize that BRAF mutations may drive the expression of these OPN-SV, as integrin receptors mediate the roles of OPN in cancer cells." (PMID 39410512, 2024). "The remaining 25–30% of CRC arise from sessile serrated lesions (SSLs) through the SSL-to-carcinoma pathways, associated with mutations in the proto-oncogene BRAF (v-raf murine sarcoma viral oncogene homolog B), MSI, and gene promoter hypermethylation (CpG island methylator phenotype)." (PMID 39066110, 2024). "In case of carcinoma PTC, genetic workup especially for a BRAF V600E mutation may pave the way to an optimized degree of thyroid and lymph node resection." (PMID 39449865, 2024). "Survival analyses of patients with early-stage (stages I to III) CRC showed that patients with a BRAF-mutated cancer had a decreased overall survival compared to those without the mutation." (PMID 38136294, 2023). "Motivated by the role of Wnt signaling in stem cells and cancer, we evaluated whether dual targeting of BRAF and Wnt could block cancer stemness." (PMID 37791907, 2023). "To address this gap, we assessed the prognostic and predictive value of vitamin C in patients with stage IV CRC by comparing vitamin C level between cancer-free and cancer patients and analyzing the specific plasma vitamin C levels in RAS (NRAS/KRAS) and BRAF mutated CRC patients." (PMID 36969825, 2023). "Although signaling proteins in the mitogen-activated protein kinase (MAPK) pathway are not frequently mutated, some TNBC cancers do contain oncogenic mutations in KRAS or BRAF." (PMID 37627272, 2023). "For example, activating mutations in KRAS, BRAF, and PI3KA, commonly detected in many cancers, may play a role in immune escape through the upregulation of programmed cell death ligand-1 and immunosuppressive cytokines." (PMID 37190307, 2023). "While generally infrequent, oncogenic deletions within MAP2K1 exons 2 and 3 are enriched in a small subset of human cancers including certain melanocytic lesions and particularly pediatric LCH (~30% of cases), and are mutually exclusive from the BRAF V600E variant." (PMID 37079639, 2023). "The assessment of EU-TIRADS, BRAF and miRNAs jointly could identify all 13 rFNA-negative cancers in the AUS-other group and 13 out of 14 (92.9%) cancers in the AUS-nuclear group." (PMID 37686562, 2023). "Right-sided cancers are associated with higher rates of microsatellite instability (MSI), more frequent aberrant activation of the EGFR pathway including higher BRAF and PIK3CA mutation rates, and increased mutational burden compared to cancers in other locations." (PMID 38062443, 2023).
cancer (continued). "Growing evidence shows that oncogenic mutations (e.g., BRAF and RAS mutations) cause numerous alterations in the expression of genes implicated in cell cycle control, migration, differentiation, and cancer stem cells, all of these are important for NSCLC pathogenesis and treatment resistance." (PMID 36770806, 2023). "Beyond YAP1-amplified malignancies, the concurrent inhibition of YAP-TEAD and MEK-RAF pathways demonstrated synthetic lethality in tumors harboring BRAF or RAS mutations, suggesting the promise of this strategy across a wide range of cancers, particularly melanoma and non-small cell lung cancer." (PMID 38067201, 2023). "An increase in IL-8 associated with BRAF mutation has been demonstrated to be essential for the induction of MMP-2 and MMP-9 that contribute to cell migration and to angiogenesis enhancing cancer vascularization to support the oxygen retrieval and nutrient supply to cancer cells." (PMID 37627054, 2023). "In this study, vemurafenib and cobimetinib will be used to treat BRAF positive cancer patients." (PMID 37686423, 2023). "RKO cells are another multi-driver cancer cell model resistant to BRAF treatment." (PMID 38136350, 2023). "The oncogenic BRAF kinase dysregulates the ERK signaling pathway in various human cancers." (PMID 38001644, 2023). "Furthermore, TERT promoter mutations cooperate with TPP1 promoter nucleotide changes to lengthen telomeres and with mutated BRAF and FGFR3 oncoproteins to enhance oncogenic signalling in cancer cells." (PMID 38033865, 2023). "In the current study, we analyzed the function of the BRAF L525R mutation, which was not registered in the Catalog of Somatic Mutations in Cancer (COSMIC)." (PMID 36856908, 2023). "When considering its associated molecular deregulation with BRAF mutations, the global literature on cancers differentiates the frequent class I BRAFv600 mutants and class II mutations from class III BRAF mutations because of their independence from NF1/RAS deregulation." (PMID 36831610, 2023). "Combining TSR with BRAF or MSI, markers which have previously been introduced to daily diagnostics but are not yet fully implemented, seems to improve the risk evaluation for cancer recurrence or metastasis." (PMID 37344790, 2023). "In recent years, progress has been made in improving patient outcomes and extending the survival of patients with BRAF‐mutant cancers relative to standard‐of‐care chemotherapeutic approaches using a targeted approach towards inhibition of the kinase activity of BRAF V600 mutants." (PMID 37775918, 2023). "Indeed, therapy with anti-EGFR drugs removes RAS/BRAF-sensitive clones of the wild type (RAS/BRAF-wt), and the obtained RAS mutation-resistant clones become the majority population of cancer cells." (PMID 37927605, 2023). "All tumors detected with BRAF V600E and/or TERT promoter variants, whether at low or high VAFs, received a definitive cancer diagnosis." (PMID 37505499, 2023). "The anti‐cancer effect of vitamin C is shown to be medicated by directing BRAF mutation or even regardless of targeting BRAF mutation." (PMID 37246589, 2023). "To verify whether CTC-like cells were truly cancer cells, we performed single-cell mutation analyses of the KRAS, BRAF, and PIK3CA genes." (PMID 36672711, 2023). "The presence of TERTp mutations, with or without BRAF mutations, has been shown to confer a risk of cancer recurrence of >40%." (PMID 37374164, 2023). "Regarding RAF1, RAF1 mutations are very rare in contrast to BRAF mutations, and it has yet to be determined whether RAF1 mutations constitute oncogenic drivers in human cancers." (PMID 38137485, 2023).